HIPK2 (homeodomain interacting protein kinase 2)
Diseases named in the same sentence as HIPK2 in open-access papers (continued):
Sharing a sentence is not in itself a finding about the gene and the disease.
thyroid cancer (6 papers, 2011 to 2024). "In contrast, the loss of HIPK2 protein expression has been initially described with aggressive behavior and tumor progression in colorectal and thyroid cancers." (PMID 28607924, 2017). "In particular, genetic loss at HIPK2 locus 7q32-34 was found by loss of heterozigosity (LOH) analysis in thyroid cancer cells stained with Gal-3 and retrieved by Laser Capture Microdissection (LCM)." (PMID 22889244, 2012). "In particular, it has been reported that HIPK2 loss-of-heterozygosity occurs frequently in radiation-induced mouse lymphomas and in human thyroid carcinomas, indicating that loss of a single allele is sufficient to impact tumor susceptibility, at least in some contexts." (PMID 25868975, 2015). "In another preliminary study, HIPK2 gene expression was analyzed in a panel of 14 thyroid carcinomas and a 3 to 10-fold reduction in its mRNA expression levels was observed in 8 of them." (PMID 21698151, 2011). "HIPK2 may undergo to some mutations, and another intriguing mechanism of HIPK2 inhibition is the reported LOH in well differentiated thyroid carcinomas and in mice." (PMID 22889244, 2012). "One may hypothesize that the combination of analysis of these two protein markers, namely HIPK2 and Gal-3, would be helpful in ameliorating the preoperative recognition of thyroid cancer." (PMID 21698151, 2011). "Therefore, HIPK2 can be considered as a new tumour suppressor gene for thyroid cancers." (PMID 21698151, 2011).
chronic kidney disease (5 papers, 2022 to 2024). Impairment of the renal function secondary to chronic kidney damage persisting for three or more months. "HIPK2 is a multifunctional kinase that acts as a key pathogenic mediator of chronic kidney disease and fibrosis." (PMID 38512421, 2024). "It has been reported that HIPK2 play an important role in kidney disease, including kidney fibrosis, the progression of acute kidney injury to chronic kidney disease and so on." (PMID 38186203, 2024). "The expression of HIPK2 increased in vancomycin‐induced acute kidney injury mouse model and inhibition of HIPK2 could attenuate the vancomycin drove the progression of acute kidney injury to chronic kidney disease." (PMID 38186203, 2024).
diabetes (5 papers, 2017 to 2024). "The findings of HIPK2-mediated IPF1/PDX1 regulation highlight the key role of HIPK2 in glucose homeostasis in patients with diabetes." (PMID 37345014, 2023). "Intriguingly, it has been shown that the high protein levels of HIPK2 in a mouse model of diabetes depend on the downregulation of E3 ubiquitin ligase Siah-1 (seven in absentia homolog-1), which is known to induce HIPK2 protein degradation." (PMID 37345014, 2023).
idiopathic pulmonary fibrosis (5 papers, 2015 to 2023). Idiopathic pulmonary fibrosis (IPF) is a nonneoplastic pulmonary disease that is characterized by the formation of scar tissue within the lungs in the absence of any known cause. "Loss of heterozygosity (LOH) at the HIPK2 locus 7q32.34 has been reported in human lung fibroblasts of patients affected by idiopathic pulmonary fibrosis (IPF) in which HIPK2 was found to be downregulated." (PMID 37345014, 2023). "Another recent study implicated dysregulated HIPK2 levels in idiopathic pulmonary fibrosis (IPF)." (PMID 25421593, 2015). "In the fibrotic area of a mouse model of bleomycin-induced pulmonary fibrosis, HIPK2 expression was found to be downregulated." (PMID 36831402, 2023). "Results from study on idiopathic pulmonary fibrosis (IPF) patients demonstrated that HIPK2 expression in IPF-derived fibroblasts is significantly lower compared with normal counterparts." (PMID 31915028, 2020). "Recently, HIPK2 has also been identified as a key regulator in idiopathic pulmonary fibrosis (IPF) and kidney fibrosis." (PMID 25421593, 2015). "However, a few studies have also started to show HIPK2 involvement in idiopathic pulmonary fibrosis (IPF), in cardiac and in liver fibrosis." (PMID 36831402, 2023). "The involvement of HIPK2 in pulmonary fibrosis has reported so far in few studies." (PMID 36831402, 2023). "Interestingly, circular (circ)HIPK2 expression was found to be increased in fibroblasts of a model of silica-induced pulmonary fibrosis." (PMID 36831402, 2023). "The authors found that lentiviral overexpression of HIPK2 counteracts the effect of bleomycin, reduces mouse lung fibroblast (MLF) proliferation and migration, and induces their apoptosis, suppressing pulmonary fibrosis." (PMID 36831402, 2023).
myocardial infarction (5 papers, 2022 to 2023). Gross necrosis of the myocardium, as a result of interruption of the blood supply to the area, as in coronary thrombosis. "The same authors reported that exercise downregulates HIPK2, and that HIPK2 inhibition by lentiviral vectors protects from myocardial infarction attenuating cardiomyocyte apoptosis induced by oxygen glucose deprivation/reperfusion (OGD/R)." (PMID 36831402, 2023). "In myocardial infarction, exercise reduces HIPK2 protein level, leading to the prevention of cardiomyocytes apoptosis and elevation of cardiac function." (PMID 37268944, 2023). "miR-147 was shown to be downregulated after hypoxia in rat cardiomyocytes and, in vivo, in a rat model of myocardial infarction; overexpression of this miRNA preserves cardiac function by silencing homeodomain interacting protein kinase 2 (HIPK2)." (PMID 35326433, 2022). "Researchers have also reported that exercise attenuates cardiomyocyte apoptosis and protects against myocardial infarction by suppressing HIPK2." (PMID 36553510, 2022).
pilocytic astrocytoma (5 papers, 2013 to 2023). Pilocytic astrocytoma is a rare subtype of low-grade glioma of the central nervous system characterized by a well circumscribed, often cystic, brain tumor with a discrete mural nodule and long, hair-like projections that extend from the neoplastic astrocytes. "The increased expression of HIPK2 was reported in sporadic pilocytic astrocytoma, likely due to the copy number gain." (PMID 34065786, 2021). "HIPK2 amplification had been detected in pilocytic astrocytomas and HIPK2 overexpression in U87 human glioma cells resulted in enhanced cell growth." (PMID 27096627, 2016). "For example, in pilocytic astrocytoma, the HIPK2 gene is frequently amplified and HIPK2 over-expression stimulates cell growth." (PMID 23805307, 2013). "Increased HIPK2 expression with or without gene amplification has been observed in pilocytic astrocytoma, cervical, and renal carcinomas, while HIPK2-mediated protection against genotoxic insults has been found in NRF2-overexpressing tumor cells." (PMID 32093146, 2020).
acute kidney injury (4 papers, 2022 to 2024). Sudden and sustained deterioration of the kidney function characterized by decreased glomerular filtration rate, increased serum creatinine or oliguria. "The HIPK2 c-terminal domain is anti-inflammatory and attenuates acute kidney injury in murine models." (PMID 38512421, 2024). "The induction of HIPK2-CT overexpression in kidney tubular cells attenuated p65 nuclear translocation, expression of inflammatory cytokines, and macrophage infiltration in the kidneys of mice with unilateral ureteral obstruction and LPS-induced acute kidney injury." (PMID 38512421, 2024).
diabetic foot ulcers (4 papers, 2023 to 2025). "On the other hand, the upregulation of HIPK2 correlates with reduced angiogenesis and impaired wound healing, aggravating diabetic foot ulcers, a condition that can be ameliorated by treatment with miR-221-3p, which targets and inhibits HIPK2." (PMID 37345014, 2023). "Thus, HG-increased HIPK2 expression correlates with reduced angiogenesis and impaired wound healing, aggravating diabetic foot ulcers, a condition that can be ameliorated by treatment with miR-221-3p." (PMID 37345014, 2023).
melanoma (4 papers, 2020 to 2021). A malignant, usually aggressive tumor composed of atypical, neoplastic melanocytes. "It was reported that HIPK2 was the tumor suppressor, while SEH1L was correlated with the time of disease-free status in melanoma." (PMID 32640634, 2020). "Thus, we can propose that inhibition or activation of the protein kinases such as AKT, HIPK2, AMPK, MET, JNK, HIF-1α, and CD44 by treatment with CDPs in the mouse melanoma model could involve the blocking of the substrate binding site as a molecular mechanism." (PMID 32793477, 2020).
osteosarcoma (4 papers, 2012 to 2024). A usually aggressive malignant bone-forming mesenchymal neoplasm, predominantly affecting adolescents and young adults. "HIPK2 phosphorylates CtBP1 and cause its degradation, thereby inducing the expression of proapoptotic genes in osteosarcoma cells." (PMID 33613771, 2021). "Similar to many other cancer types, the osteosarcoma cells and biopsies showed significantly decreased expression of HIPK2, whereas its overexpression suppressed cell viability and increased chemosensitivity following CDDP and MTX treatments." (PMID 33613771, 2021). "In the present study, we investigated the role of HIPK2 in the tumorigenesis of osteosarcoma by determining its expression level in osteosarcoma cells and biopsies." (PMID 33613771, 2021). "We observed a significant decrease in the expression levels of HIPK2 and phosphorylated CtBP1 in both osteosarcoma cells and biopsies and an opposite response in the CtBP1 expression level." (PMID 33613771, 2021). "The findings presented here revealed a significant downregulation of HIPK2 in both osteosarcoma cell lines and biopsies, as well as an impairment of CtBP1 phosphorylation and a consequent accumulation of CtBP1." (PMID 33613771, 2021). "By contrast, the levels of phosphorylated CtBP1 and HIPK2 protein levels were decreased in osteosarcoma cells and they showed the similar patterns in the same osteosarcoma cells." (PMID 33613771, 2021). "We then determined the protein levels of CtBP1, pCtBP1, CtBP2 and HIPK2 in osteosarcoma cells and biopsies." (PMID 33613771, 2021). "We examined whether the overexpression of CtBP1 mRNA and protein levels in osteosarcoma cells was directly regulated by HIPK2 by generating HIPK2-overexpression (OE) cell lines in hFOB1.19, MG63 and Saos2 backgrounds." (PMID 33613771, 2021). "The expression of HIPK2 was dramatically decreased in osteosarcoma biopsies." (PMID 33613771, 2021). "Taken together, our in vitro and in vivo results revealed that overexpression of HIPK2 could remove the CtBP1-mediated transrepression of proapoptotic genes, indicating a new therapeutic option for the treatment of osteosarcoma." (PMID 33613771, 2021). "HIPK2 functions as a tumor suppressor in osteosarcoma cells; therefore, we speculated that its overexpression should inhibit osteosarcoma cell growth." (PMID 33613771, 2021). "The observation that overexpression of HIPK2 could inhibit osteosarcoma cell growth in vitro and in vivo prompted us to determine the gene expression changes following HIPK2 overexpression." (PMID 33613771, 2021). "However, the promising result observed here that HIPK2 overexpression can inhibit osteosarcoma cell growth in vitro and in vivo suggests that HIPK2 may be a therapeutic target for the treatment of osteosarcoma." (PMID 33613771, 2021). "Therefore, we speculated that knockdown of HIPK2 in hFOB1.19 cells should reduce proapoptotic gene expression as that in osteosarcoma cells, while overexpression of HIPK2 in hFOB1.19 cells should induce proapoptotic gene expression." (PMID 33613771, 2021). "We investigated the possible involvement of HIPK2 in the regulation of CtBP1 by examining the mRNA level of HIPK2 in the hFOB1.19 human osteoblast cell line and in the DAN, MG63, HOS, T1-73, 143B, Saos2, and U2OS osteosarcoma cell lines." (PMID 33613771, 2021). "Although we identified a HIPK2-mediated phosphorylation mechanism in the present study, the mechanism for transcriptional regulation of CtBP1 in osteosarcoma cells is not known." (PMID 33613771, 2021). "However, the expression status of HIPK2 in osteosarcoma cells is not known, and a role for HIPK2 in the phosphorylation of CtBP1 and tumorigenesis remains to be established in osteosarcoma." (PMID 33613771, 2021). "We also determined whether osteosarcoma biopsies had the similar expression patterns for CtBP1, CtBP2 and HIPK2 in 20 osteosarcoma biopsies and their adjacent noncancerous tissues." (PMID 33613771, 2021).
osteosarcoma (continued). "However, whether HIPK2 functions as a tumor suppressor that phosphorylates CtBP1 to promote the tumorigenesis of osteosarcoma is not known." (PMID 33613771, 2021). "However, a role for HIPK2 in these processes has not been established for osteosarcoma." (PMID 33613771, 2021). "However, HIPK2 expression did not induce apoptosis nor sensitized MNSC SHEP NB cells to bleomycin, while it was clearly sufficient to lead U2OS osteosarcoma cells to death." (PMID 23152863, 2012).
Parkinson disease (4 papers, 2015 to 2024). A progressive degenerative disorder of the central nervous system characterized by loss of dopamine producing neurons in the substantia nigra and the presence of Lewy bodies in the substantia nigra and locus coeruleus. "GSEA analysis demonstrated significant associations between HIPK2 and DDRGK1 with ribosome, Parkinson’s disease, oxidative phosphorylation, and other pathways." (PMID 39022342, 2024). "HIPK2 has been involved in several neurodegenerative diseases, such as Parkinson, Alzheimer, and Lafora disease, mainly because of its role in proapoptotic induction." (PMID 33043004, 2020). "In this instance, we observed that in Purkinje cells the lack of Hipk2 negatively interferes with Wnt/β-catenin proper function, giving rise to an impaired degradation of β-catenin – a hallmark of Parkinson's disease, spinocerebellar ataxia, and other neurodegenerative diseases." (PMID 26633710, 2015).
prostate carcinoma (4 papers, 2017 to 2024). A carcinoma that arises from epithelial cells of the prostate gland. "Similarly, the initial 11 pathways (lysine degradation, prostate cancer, etc.)of HIPK2 were enriched in the high expression group, whereas the remaining nine pathways (glycine serine and threonine metabolism, ribosome, etc.)were enriched in the low expression group." (PMID 39022342, 2024).
acute promyelocytic leukemia (3 papers, 2017 to 2025). An aggressive form of acute myeloid leukemia (AML), characterized by arrest of leukocyte differentiation at the promyelocyte stage, due to a specific chromosomal translocation t(15;17) in myeloid cells. "The circRNA circHipk2 originates from exon 2 of the Hipk2 gene in mice and was reported to be involved in acute promyelocytic leukemia and myocardial injury." (PMID 34066653, 2021). "In acute promyelocytic leukemia, ATRA induced differentiation and altered 508 circRNAs, including circ‐HIPK2, which sponges miR‐124‐3p to regulate MAPK1." (PMID 40796179, 2025).
Alzheimer disease (3 papers, 2010 to 2024). A progressive, neurodegenerative disease characterized by loss of function and death of nerve cells in several areas of the brain leading to loss of cognitive function such as memory and language.
bladder cancer (3 papers, 2014 to 2020). "On the other hand, homeodomain interacting protein kinase 2 (HIPK2) was identified in bladder cancer with transitional cell carcinoma lymphatic metastasis." (PMID 32640634, 2020). "By contrast, another study found that in bladder cancer metastasis, downregulation of HIPK2 induced EMT and cell invasion." (PMID 29208636, 2018). "Our studies provide a rationale for the potential use of HIPK2 transduction to sensitize chemoresistant bladder cancer cells to cisplatin." (PMID 24846322, 2014). "Here we found that upregulation of HIPK2 inhibits Wip1 expression, which sensitizes chemoresistant bladder cancer cell to cisplatin." (PMID 24846322, 2014). "Forced expression of HIPK2 sensitizes chemoresistant bladder cancer cell to cisplatin by regulating Wip1 expression." (PMID 24846322, 2014). "In the present study, we found that HIPK2 mRNA and protein levels are significantly decreased in cisplatin-resistant bladder cancer cell in vivo and in vitro." (PMID 24846322, 2014). "Based on the results of survival analysis, HIPK2 could be an important gene in bladder cancer with transitional cell carcinoma lymphatic metastasis." (PMID 32640634, 2020). "Based on these findings, we investigated whether HIPK2 regulates chemosensitivity by targeting Wip1 in bladder cancer cell." (PMID 24846322, 2014). "Importantly, we demonstrated that HIPK2 negatively regulates Wip1 expression in bladder cancer cell." (PMID 24846322, 2014). "Finally, we demonstrated that overexpression of HIPK2 sensitizes chemoresistant bladder cancer cell to cisplatin by regulating Wip1 expression." (PMID 24846322, 2014).
cervical cancer (3 papers, 2013 to 2023). A primary or metastatic malignant neoplasm involving the cervix. "Furtermore, the expression of HIPK2 kinase was meaningfully lower in cases of cervical cancer in stage I than cases of cervical cancer in stage II or III, showing a connection between HIPK2 and cancer development." (PMID 37047552, 2023). "HIPK2 has been reported to be overexpressed in cases of cervical cancer." (PMID 37047552, 2023). "HIPK2 protein expression in cervical cancer gradually increases along with disease progression in intraepithelial cervical neoplasia, carcinoma in situ, and invasive cervical cancer, implicating the contribution of HIPK2 to the tumor development and progression of uterine cervical neoplasms." (PMID 28607924, 2017). "Moreover, strong HIPK2 immunostaining in cervical cancer tissues was hypothesized to correlate with tumour progression." (PMID 23805307, 2013).
diabetic retinopathy (3 papers, 2021 to 2023). "Intriguingly, deregulated angiogenesis in human retinal endothelial cells (hREC), by means of activation of the HIF-1/VEGF pathway upon miR-423-5p-induced HIPK2 downregulation in diabetic patients, contributes to diabetic retinopathy." (PMID 37345014, 2023).
focal segmental glomerulosclerosis (3 papers, 2016 to 2023). A renal disorder characterized by sclerotic lesions in the glomeruli. "Interestingly, HIPK2’s role was confirmed in focal segmental glomerulosclerosis (FSGS), diabetic nephropathy and IgA nephropathy (IgAN), with the latter being the most prevalent primary human glomerulonephritis." (PMID 36831402, 2023). "The authors confirmed the role of HIPK2 in inducing kidney fibrosis and also in focal segmental glomerulosclerosis (FSGS), DN, and IgA nephropathy (IgAN)." (PMID 37345014, 2023).